MYC (MYC proto-oncogene, bHLH transcription factor)
Diseases named in the same sentence as MYC in open-access papers (continued):
Sharing a sentence is not in itself a finding about the gene and the disease.
cancer (continued). "The potential impact of PRMT5 inhibition on MYC makes it an attractive target in various cancers." (PMID 38136401, 2023). "Research indicates that approximately 70% of human cancers involve dysregulated MYC expression." (PMID 37669923, 2023). "LINRIS can induce the K139 ubiquitination of IGF2BP2, thus preventing the degradation of IGF2BP2 by lysosomes, which keeps the content of IGF2BP2 protein at a certain level, and promotes the glycolysis and proliferation of cancer cells through the IGF2BP2/MYC/glycolysis axis." (PMID 37582735, 2023). "Nowadays, theoretically, targeting MYC is an attractive strategy for cancer treatment." (PMID 37968308, 2023). "Given that mitochondrial dysfunction is typically associated with mitochondrial oxidative stress, we measured the levels of PRX3, a mitochondrial antioxidant protein induced by oxidative stress and elevated in various cancers, and a target gene of the oncogene MYC." (PMID 37047426, 2023). "Hence, these findings indicated that the anti-cancer activity of JOA against K562 cells was also likely originated from the inhibition of BCR-ABL/c-MYC signaling." (PMID 37215441, 2023). "This provides an attractive target for cancer therapy, primarily in MYC-amplified tumors." (PMID 37443779, 2023). "Clearly, MYC is very important for cancer cell survival and can directly enhance cancer stemness." (PMID 36765885, 2023). "Meanwhile, we found that c-MYC S405A cancer cells had lower proliferation ability, cellular ATP level, and DNA replication ability than c-MYC WT cancer cells, while c-MYC S405E cancer cells had higher proliferation ability, cellular ATP level, and DNA replication ability than c-MYC WT cancer cells." (PMID 37596667, 2023). "Additionally, MYC has been shown to protect cancer cells from radiation-induced DNA damage and apoptosis, while inducing DNA repair in response to radiation." (PMID 37755397, 2023). "We and others previously showed that MYC disrupts molecular clock oscillation in cancer cells, but the reasons for this, and what potential benefit cancer cells might gain, remained unclear." (PMID 37639465, 2023). "To investigate whether MYC exhibited distinct behavior in these additional cancer types, we utilized ALAN to examine the MYC network signature in each context." (PMID 37059746, 2023). "MYC is a well-described oncogene across multiple cancer types." (PMID 37173990, 2023). "MYC was highly expressed in cancer tissues as was TAF10 at the protein level." (PMID 36639831, 2023). "Proliferation of cancer cells can be boosted by the simultaneous expression of MYC and PVT1." (PMID 36624401, 2023). "In fact, MYC aberrations or upregulation of MYC-related pathways occur in many cancers." (PMID 37998757, 2023). "Thus, our results and those of others point at MYC downregulation as a means to achieve an optimal antitumor response in KRAS-driven cancers." (PMID 37816716, 2023). "Finding the right formulation to target MYC-dependent cancers and to achieve a high intracellular concentration of compounds blocking or attenuating oncogenic MYC activities could be as important as the development of novel MYC-inhibiting principles." (PMID 36969025, 2023). "MYC stimulates cancer development through activating critical positive cell-cycle regulators, such as cyclins (cyclins D, E, A and B1), CDKs (CDK1, 2, 4 and 6) and E2F transcription factors (E2F1, 2 and 3), or by antagonizing cell-cycle repressors, such as p15, p21 and p27." (PMID 36765885, 2023). "MYC contributes to the development of many human cancers, and targeted therapies against MYC may be one of the most effective cancer treatments available today." (PMID 37215074, 2023). "Therefore PVT1 is a promising target for the treatment of MYC-driven cancers via indirect influence on this transcription factor." (PMID 38203731, 2023).
cancer (continued). "RiBi overoccurrence is a controllable target of cancer; rRNA accounts for about 80% of total RNA and RiBi requires a large number of nucleotides, mTORC1 or c-MYC oncogenic signaling pathway overactivation while upregulating RiBi and nucleotide de novo synthesis." (PMID 38002277, 2023). "This section discusses the mechanisms by which MYC supports immune evasion in cancer." (PMID 37755397, 2023). "MYC could trigger immediate and reversible cancer-driven signals, making it compelling to specify the regulatory mechanisms of the MYC gene." (PMID 37828515, 2023). "MYC is relevant to cancer development because of its involvement in oncogenic signaling." (PMID 38137511, 2023). "Hence, there is a need to prioritize the synthetic lethality vulnerabilities which offer the greatest therapeutic outcome against specific MYC‐driven cancers." (PMID 36684069, 2023). "In preclinical studies, MYC is a well-known Brd4 target gene in multiple cancer types." (PMID 37049806, 2023). "MYC activation leads to manifestation of many hallmarks of cancer involved in cancer growth." (PMID 36941257, 2023). "MYC is dysregulated and overexpressed in most human cancers." (PMID 37444499, 2023). "Moreover, STAT3 cooperates with NF-κB in IL-6 induction and the IL-6/STAT3 pathways synergize in the induction of c-MYC leading to promoting cancer cell survival." (PMID 37480115, 2023). "Therefore, in MYC-driven tumors, targeting MYC-associated chromatin interactions, MYC expression, effector function, specific proteasomal degradation, and the MYC regulatory RNAs or taking advantage of synthetic lethal interactions may represent potential new strategies for cancer therapy." (PMID 37443779, 2023). "Previous studies recognized MYC as a critical substrate of PP2A complex in cancer." (PMID 37891368, 2023). "MYC is a proto-oncogene that can improve the performance of oncogenic transcription amplification, is one of the most highly amplified oncogenes in numerous human cancers, and is a significant target of cancer therapy." (PMID 36873736, 2023). "Therefore, JQ1 or other BET inhibitors represent promising compounds to treat MYC-dependent cancers." (PMID 36969025, 2023). "Many cancers display dysregulated expression of the MYC gene." (PMID 38136334, 2023). "A recent report analyzing somatic copy-number alterations (SCNAs) across human cancers has identified 76 amplification regions that are altered at a significant frequency across multiple cancer types, and the most frequent of these focal SCNAs is MYC amplifications." (PMID 37755397, 2023). "Successfully blocking MYC function remains a holy grail for human cancer treatment." (PMID 36765784, 2023). "Undoubtedly, a therapeutic strategy that targets MYC can initiate a new era of cancer treatment." (PMID 36966168, 2023). "In contrast to other proto-oncogenes whose carcinogenic functions invariably depend on mutation, MYC is either over-expressed or amplified in human cancer, but it does not acquire gain of function by mutation." (PMID 37755396, 2023). "It has been shown that mutation in both MYC and RBPs (RNA Binding proteins) causes apoptosis, whereas single gene mutation either in MYC or RBPs, does not affect the growth of cancer cells." (PMID 37469704, 2023). "Indeed, the Authors of the CYCLOPS study noted that since GLUT2 is only weakly rhythmic in HCC, a cancer often driven by MYC, the use of the GLUT2-targeting streptozocin should be timed to minimize dose-limiting toxicity in the liver and kidney." (PMID 37639465, 2023). "Recent promising studies highlighted that partial depletion or inhibition of MYC may be sufficient for treatment of MYC-dependent cancers and other diseases." (PMID 37941901, 2023).
cancer (continued). "Furthermore, we summarize current possibilities to deliver appropriate drugs into cancer cells containing derailed MYC using viral vectors or appropriate nanoparticles." (PMID 36969025, 2023). "MYC is a transcription factor that acts as a proto-oncogene in many cancers." (PMID 37894282, 2023). "MYC is one of the most frequently dysregulated oncogenes in human cancer." (PMID 36897988, 2023). "Both genes have annotations related to cancer and both have functional links to MYC regulation." (PMID 38133254, 2023). "Indeed, enhancement of MYC transcriptional activity by TAF10 signalling promotes cell proliferation in cancer cells." (PMID 36639831, 2023). "MYC is one of the most commonly activated oncogenes that mediate cancer initiation and progression." (PMID 36960074, 2023). "Indeed, the diversity and sheer number of genes having the potential to become dysregulated upon MYC alteration place MYC proteins at the top of the list for targeted anti-cancer therapy pursuits." (PMID 37336886, 2023). "Transformation by the proto-oncogene MYC causes dysregulation of the pre-mRNA splicing reaction in cancer, but it is not known how mRNA isoform changes are directed by MYC." (PMID 37399401, 2023). "Upon activation by norepinephrine, ATF1 potentiates cancer stemness by coordinated trans-activation of both nuclear pluripotency factors MYC/NANOG and mitochondrial biogenesis regulators NRF1/TFAM, thereby orchestrating nuclear reprograming and mitochondrial rejuvenating." (PMID 37463926, 2023). "We have previously found that the correlation between SCNA and gene expression is higher for cancer driver genes that are frequently amplified and identified co-dependencies between amplification of MYC and genes from the PI3K pathway which have therapeutic potential." (PMID 37166279, 2023). "With more study, it may be possible to provide proof of concept that targeting MYC by inhibiting its translation is a potential treatment for patients with FLC or other PKA-driven cancers, for whom few options currently exist." (PMID 36692000, 2023). "Several lncRNAs have been found to influence cancer progression by interacting with MYC." (PMID 37204526, 2023). "The deregulation of many cellular actors leads to the uncontrolled proliferation and survival of cancer cells, for example, the overexpression of oncogenes such as MYC, a transcription factor that drives the expression of genes involved in cell proliferation and survival." (PMID 37047814, 2023). "Indeed, we detected significant (Bonferroni-corrected p < 0.05) upregulation of MYC and E2F targets, as well as G2M (cell cycle phase following S phase) in MBs, ATRTs, and HGGs compared with several other cancer groups." (PMID 37492101, 2023). "Moreover, it is not currently known if the genome instability induced by CDK7i is broadly applicable to cancers of multiple lineages or if this effect is restricted to SCLC or cancers that are dependent on MYC, such as HCC." (PMID 37201585, 2023). "Furthermore, MYC signaling in cancer cells enables abnormal TME regulation and evasion of the host immune response." (PMID 36959802, 2023). "In this regard, Omomyc, a newly developed MYC inhibitor is more specific in targeting MYC-related genes responsible for cancer development than other MYC inhibitors, might provide insights into how to target MYC for cancer therapy." (PMID 37998757, 2023). "Furthermore, in vitro studies have shown that 1 can reduce telomerase activity, decrease c-MYC and hTERT expression, and inhibit cancer cell growth." (PMID 36979947, 2023). "MYC amplification is also found in HRp cancer and correlates with increased RS." (PMID 37842243, 2023). "MYC regulates the cancer metabolism and promotes glycolysis." (PMID 36769322, 2023).
cancer (continued). "c-MYC has long been proposed to play a functional role in the pathophysiology of cancer." (PMID 38078012, 2023). "Targeting MYC may enhance cancer cell sensitivity to DNA damage and serve as a potential strategy for anticancer therapy." (PMID 37755397, 2023). "In addition, AARS2 also displayed the consensus and same biological activity across almost all cancers, which harbored conspicuous positive relationship with proliferation‐related pathways such as G2M checkpoint, Wnt/β‐catenin pathway, and MYC Targets V2." (PMID 37990642, 2023). "Since HuR is necessary for the activation of many oncogenes, including MYC 44, down-regulation in HuR protein levels or inhibition of HuR activity are with significant value, suggesting HuR as a promising therapeutic target in cancer." (PMID 37151387, 2023). "Moreover, MYC-amplified cancer cells were reported to be particularly sensitive also to splicing inhibitors." (PMID 37599362, 2023). "Notably, SOX2, OCT4, KLF4, and the pluripotency reprogramming facilitator c-MYC, known for their role in establishing and maintaining stem cell pluripotency, are also aberrantly expressed in certain cancer cells." (PMID 37760529, 2023). "Furthermore, it is unlikely that inhibition of each synthetic lethality target is equal in different cancer types where MYC drives pathogenesis." (PMID 36684069, 2023). "Through computational simulation, we identified miR-26a bound to the 3′UTR of GSK3β/MYC/CCND1, thus suggesting a close association of Met/GSK3β/MYC/CCND1 and miR-26a promoting cancer proliferation, invasion, migration, drug resistance, and stemness metastasis in CRC patients." (PMID 36672275, 2023). "Importantly, the MYC oncogene uniquely coordinates key processes by which cancer cells evade the immune system." (PMID 36897988, 2023). "Functional studies and gene expression determination confirm that MIAT knockdown not only affects short- and long-term survival and the apoptosis of leukemic cells but also plays a pivotal role in the alteration of key genes involved in cancer, including c-MYC and HIF-1A." (PMID 37624039, 2023). "Consequently, inhibiting the MYC–WDR5 interaction has been shown to induce the regression of malignant tumors, offering an alternative approach to targeting MYC in the development of anticancer drugs." (PMID 37568727, 2023). "As direct targeting of MYC in cancer thus far has been unsuccessful because of its complex structure and pleiotropic functions, the identification of key cofactors for MYC to target at transcriptional or translational levels has emerged as a promising alternative for the indirect inhibition of MYC." (PMID 37190167, 2023). "Interestingly, pan-cancer analysis showed that MYC amplification is mutually exclusive with many canonical oncogenic drives such as PIK3CA, PTEN, APC, and BRAF." (PMID 37601651, 2023). "MYC plays a valuable role in almost every stage of oncogenesis by orchestrating proliferation, differentiation and metabolism, and its blockade has been widely explored for the treatment of cancer." (PMID 37608281, 2023). "While the role of MYC in regulating metabolism has been extensively studied over three decades, it is unclear whether metabolism may reciprocally regulate MYC to support its enhanced abundance in cancer." (PMID 37130865, 2023). "Our findings that MYC shifts certain metabolic and cell-attachment pathways from being oscillatory to being up- or down-regulated is supported by observations of similar phenomena from human cancer samples." (PMID 37639465, 2023). "To assess whether MYC expression affects the abundance of sialoglycans on cancer cells, we used a periodate-aminooxy ligation to quantify sialic acids on the surface of MYC-driven T-ALL cells in the MYC on (no doxycycline) and off states (plus doxycycline)." (PMID 36897988, 2023).
cancer (continued). "In order to investigate whether MYC may play a role in modulating RNAPII transcription termination activity in MYC overexpressing cancer cells, the two cell lines were stably transduced with a doxycycline-inducible, FlagOmomyc (FO) expressing lentivirus." (PMID 36830948, 2023). "In addition to the downstream effectors of YAP, ID1 and c-MYC have been defined as the markers of BCSCs because ID1( +) cells are enriched for self-renewal in tumorsphere and c-MYC drives a stem-like phenotype in cancer." (PMID 38102651, 2023). "The MYC oncogene is one of the most frequently activated cancer-driving genes." (PMID 36897988, 2023). "Our findings suggest that complex-I inhibitors such as IACS-010759 may be an attractive therapeutic strategy for treating various types of MYC-activated cancers." (PMID 37130865, 2023). "Furthermore, glutamine has been shown to be an indispensable nutrient source in many cancer types, particularly MYC-driven cancers." (PMID 36968582, 2023). "As a predominant cancer driver, MYC is an important drug target." (PMID 37755396, 2023). "Finally, USP29 ubiquitinase is a potential novel target for cancer therapy as it provides an upstream hub for MYC and HIF1α." (PMID 37443779, 2023). "The fact that the genes involved in the regulation of CSCs are all controlled by SP1, HIF-1, and MYC indicates that the very reason why these TFs are important participants of cancer regulatory networks might be because they regulate CSCs." (PMID 37998757, 2023). "This suggested that MYC amplification-driven resistance to mTOR-targeted therapies may also occur in human cancer patients." (PMID 37642941, 2023). "Often, cancer cells with an elevated MYC expression exhibit a highly proliferative phenotype." (PMID 38288105, 2023). "Notably, combination therapies have been gaining traction in cancer therapeutics against MYC due to inevitable acquired and polyclonal resistance against monotherapies." (PMID 36684069, 2023). "With an improved understanding of how MYC deregulation triggers an adapted or feedback mechanism in cancer cell metabolic signaling, our findings may provide new mechanistic insights and alternative therapeutic options for improved cancer treatment." (PMID 36632215, 2023). "Similarly, Ornithine decarboxylase (ODC1) is involved in polyamine biosynthesis and is upregulated in tumors, especially in MYC-driven cancers." (PMID 37760568, 2023). "Gene Ontology (GO) functional analysis was performed, and examination of the intersecting biological process (BP) terms enriched in all five cancer cell clusters identified the Notch signaling pathway; the core genes of this pathway, including MYC, are highlighted in red." (PMID 36879115, 2023). "Targeting MYC signaling has long been considered an effective therapeutic strategy for cancer." (PMID 37596667, 2023). "ob-aT bASCs exhibited an increased ability to stimulate cancer stemness in highly malignant MDA-MB-231 cells by enhancing the gene expression of pluripotency and CSC associated genes such as ALDH1H1, ALDH2, c-MYC, CD34, LGR5, CXCR4, SOX2 and OCT4, fueling further their malignant potential." (PMID 36710348, 2023). "ITH of seven meta-programs, related to cell cycle, stress, hypoxia, interferon responses, EMT, and MYC targets, was frequent in most cancer types, 21 meta-programs were shared only between a subset of cancer types, and the variability of the remaining meta-programs was tumor-type specific." (PMID 38188682, 2023). "MYC has been the most appealing yet challenging target among EBTFs for its centrality in cancer." (PMID 37601651, 2023). "MYC in cancer could bind to the VEGFA promoter, thereby stimulating the VEGFA production and subsequently sprouting angiogenesis." (PMID 36966311, 2023). "Indeed, MYC is found deregulated in the majority of cancers, where it controls the transcription of genes that altogether enable tumors to proliferate, thrive, and even resist to different therapies." (PMID 36765784, 2023).